WFS1 (wolframin ER transmembrane glycoprotein)
Diseases named in the same sentence as WFS1 in open-access papers (continued):
Sharing a sentence is not in itself a finding about the gene and the disease.
Wolfram syndrome (continued). "Wolfram syndrome (WS, MIM222300), caused by mutations in the WFS1 gene, is an autosomal recessive disorder most frequently characterized by diabetes insipidus, diabetes mellitus, optic atrophy, and deafness." (PMID 23914152, 2013). "These include the following antiapoptotic genes: AATF (antiapoptosis-inducing transcription factor) and WFS1 (Wolfram syndrome 1)." (PMID 20585452, 2010). "Abnormal lens morphology—mainly cataracts, was present in 8% of patients with or without optic atrophy and was mainly contributed by Wolfram syndrome or isolated cataracts caused by WFS1 variants." (PMID 39423307, 2025). "Pathogenic variants of the WFS1 gene are most commonly associated with the autosomal recessive form of Wolfram syndrome (WFS1), autosomal dominant-Wolfram-like syndrome (WFSL, MIM #614296), and WFS1-related low-frequency sensorineural hearing loss (LFSNHL, DFNA6/14/38, and MIM #600965)." (PMID 39064493, 2024). "Two causative genes, WFS1 and CISD2, have been implicated in the development of Wolfram syndrome." (PMID 37415600, 2023). "Autosomal dominant variants have previously been associated with Wolfram-like syndrome, a WFS1-related disorder with generally milder phenotypes and unlike Wolfram Syndrome, no decrease in life expectancy." (PMID 37415600, 2023). "Understanding the molecular mechanism regulating WFS1 stability might provide a potential therapeutic target for Wolfram syndrome." (PMID 37440664, 2023). "Biallelic mutations in the gene encoding WFS1 underlie the development of Wolfram syndrome (WS), a rare neurodegenerative disorder with no available cure." (PMID 37107585, 2023). "Unlike the recessively inherited Wolfram syndrome, WFS1 heterozygous variants cause DFNA6/14/38 and wolfram-like syndrome, characterized by autosomal dominant nonsyndromic hearing loss, optic atrophy, and diabetes mellitus." (PMID 37041640, 2023). "Supplementing our previous model that shows the relationship between WFS1 and ER stress-induced pancreatic β-cell death, here we provide new evidence showing that islet-localized inflammation accelerates the progression of diabetes in Wolfram syndrome." (PMID 35399956, 2022). "Wolfram syndrome (WFS) is a rare genetic syndrome inherited in an autosomal recessive manner, which occurs as a result of the presence of pathogenic variants mainly in the WFS1 gene." (PMID 34801048, 2021). "The finding of WFS1 mutations in psychiatric subjects who do not have Wolfram Syndrome led to the suggestion that these mutations are associated with psychiatric symptoms and that mutations in the gene WFS1 can be biomarkers and predictors for mood disorder." (PMID 34746052, 2021). "Taken together, WFS1 expression patterns in various brain structures could inform knowledge relevant to the neurological and psychiatric symptoms observed in Wolfram syndrome." (PMID 31796109, 2019). "Syndromes that have mutations in WFS1 but do not meet the diagnostic criteria of Wolfram syndrome (diabetes mellitus and optic atrophy) are referred to as WFS1-related disorders." (PMID 31796109, 2019). "One individual with early onset diabetes was homozygous for a rare pathogenic missense variant in the WFS1 gene but did not have the additional phenotypes associated with Wolfram syndrome." (PMID 29207974, 2017). "In the first animal model of Wolfram syndrome, the wfs1 gene was disrupted by exon 2 deletion." (PMID 28951826, 2017). "In the present study we report a 16 year-old patient with Wolfram syndrome with a therapeutically challenging form of non-autoimmune diabetes associated with a novel sequence variant in the WFS1 gene." (PMID 26819810, 2015). "Mutations in the WFS1 gene have been reported in patients with bipolar disorder, major depression, schizophrenia, and suicide victims without Wolfram syndrome." (PMID 24799886, 2014).
Wolfram syndrome (continued). "Similarly, mutations in the WFS1 gene lead to Wolfram syndrome, a severe neurodegenerative disorder characterized by diabetes insipidus, diabetes mellitus, optic atrophy, and deafness (DIDMOAD), caused by chronic endoplasmic reticulum (ER) stress and subsequent β-cell apoptosis." (PMID 41614934, 2026). "Similarly, Wolfram syndrome is a constellation of diabetes insipidus, diabetes mellitus, optic atrophy and deafness (DIDMOAD) that can be observed with pathological variants in the autosomal WFS1 and CISD2 genes." (PMID 38397177, 2024). "The most well-studied human model of UPR-associated deafness, Wolfram syndrome due to mutations in wolframin (WFS1), however, does not translate to mice, in which WFS1-KO mice have normal hearing despite exhibiting other manifestations of Wolfram syndrome, including diabetes." (PMID 37943620, 2023). "Therefore, there is a trend that the majority of recessive inactivating mutations of WFS1 cause typical Wolfram syndrome, whereas dominant non-inactivating mutations of WFS1 are associated with less severe but more heterogeneous phenotypic manifestations." (PMID 36843716, 2023). "Wolfram syndrome 1 gene (WFS1) was identified in the year of 1998 on chromosome 4p16 as a novel gene that causes a rare autosomal recessive neurodegenerative disorder, namely Wolfram syndrome (WFS) alias DIDMOAD syndrome (diabetes insipidus, diabetes mellitus, optic atrophy, and deafness)." (PMID 37859980, 2023). "Given our neuroimaging findings, suggestions from neuropathological case studies, and our WFS1 expression analyses, we propose that Wolfram syndrome could be classified as a developmental hypomyelinating condition, characterized by reduced or absent myelin development." (PMID 31796109, 2019). "No patients in our study with WFS1 variants presented with bona fide Wolfram syndrome." (PMID 31765440, 2019). "Mutations in WFS1 are usually associated with Wolfram syndrome (OMIM# 222300), sometimes known as DIDMOAD (diabetes insipidus, diabetes mellitus, optic atrophy, and deafness)." (PMID 31765440, 2019). "WFS1 was first identified as a causative gene for the autosomal recessive disorder Wolfram syndrome type 1 (MIM #222300), or DIDMOAD (diabetes insipidus, diabetes mellitus, optic atrophy, and deafness) syndrome." (PMID 29529044, 2018). "We supposed that 5-HT system may have some correlations with Wfs1 gene or wolfram syndrome." (PMID 25294992, 2014). "The patient's WFS1 mutation was verified through Sanger sequencing in a CLIA-certified laboratory, though not without complications; the initial report came back negative and only after requested follow-up was the homozygous mutation detected, thereby confirming the diagnosis of Wolfram syndrome." (PMID 22226368, 2012). "Because the proband of our study family highly benefits from his cochlear implant, this suggests that indeed there is a deleterious effect of the present WFS1 mutation in the cochlea without any neurodegenerative symptoms that are so common in Wolfram syndrome." (PMID 20069065, 2010). "Wolfram Syndrome (WFS:OMIM 222300) is an autosomal recessive, progressive, neurologic and endocrinologic degenerative disorder caused by mutations in the WFS1 gene, encoding the endoplasmic reticulum (ER) protein wolframin, thought to be involved in the regulation of ER stress." (PMID 23981289, 2013). "This was likely driven by Wolfram syndrome (WFS1), since when those cases removed, no features were significantly enriched in monogenic cases." (PMID 40746173, 2026). "This indicates that while the inactivation of the WFS1 protein is necessary for Wolfram syndrome, the mechanism of the inactivation is not clear." (PMID 37759745, 2023). "Based on the molecular characterization of WFS1 p.R558C, we hypothesized a combination treatment of 2 chemical chaperones, 4-PBA and TUDCA, could provide a treatment for Wolfram syndrome." (PMID 36134655, 2022).
Wolfram syndrome (continued). "WFS1 mutations lead to type 6/14/38 autosomal dominant non-syndromic deafness (DFNA) and Wolfram syndrome 1, an autosomal recessive neurodegenerative disease including deafness, optic nerve atrophy, and diabetes insipidus." (PMID 36570450, 2022). "It will also greatly expand our understanding of the longitudinal phenotype of WFS1-related disorders, rather than classically defined Wolfram syndrome." (PMID 30979932, 2019). "Individuals with Wolfram syndrome typically present with one or more of the main DIDMOAD symptoms, and diagnosis is confirmed by genetic testing of the WFS1 gene; the CISD2 mutation is not commonly screened for." (PMID 31366393, 2019). "A previous study of mice that lacked the Wfs1 gene showed some symptoms consistent with Wolfram syndrome, but depressive behaviors were not consistently observed." (PMID 26371507, 2015). "However, the role of inflammation in Wolfram syndrome and its relationship with WFS1 has not been fully elucidated." (PMID 35399956, 2022). "Known Wolfram syndrome genes WFS1 and CISD2 did not lie within the regions of homozygosity." (PMID 33879837, 2021). "Although there is some evidence that WFS1 is involved in Ca2+ homeostasis and influences the stability of the ER stress sensor ATF6, the exact function of WFS1, its regulation, and the molecular mechanisms linking its function to Wolfram Syndrome and type 2 diabetes are far from resolved." (PMID 23703906, 2013).
diabetes (139 papers, 2007 to 2026). "Wolfram syndrome type 1 (WS1) is a rare autosomal recessive disorder involving diabetes mellitus, optic atrophy, and neurodegeneration, caused by biallelic WFS1 mutations." (PMID 42093864, 2026). "We aim to investigate the clinical features and pathogenic mechanisms of a WFS1 missense mutation inducing atypical phenotype characterized solely by isolated diabetes mellitus (DM)." (PMID 41896889, 2026). "Sensory Deficits (Vision/Hearing): Often precede or accompany diabetes in WFS1 (Wolfram) or GLIS3 mutations." (PMID 41614934, 2026). "Subsequent studies have described other heterozygous WFS1 variants in diabetes cases, suggesting potential causality." (PMID 40779032, 2025). "Diabetes mellitus is a common clinical manifestation of disease caused by mutations in the WFS1 gene and requires further differentiation on the basis of laboratory findings." (PMID 40641032, 2025). "While previous studies have established that WFS1 mutations are causative for diabetes, limited research has been conducted on WFS1 mutations in China." (PMID 40641032, 2025). "A homozygous variant located in the WFS1 gene was identified in P7 and confirmed in the brother, who was also diagnosed with diabetes, as well as in parents, who were heterozygous for the variant." (PMID 41614819, 2025). "In this study, we discovered the vicious cycle of zinc transportation and cellular stress driving pancreatic β cell loss in diabetes regulated by WFS1–ZnT8–zinc axis." (PMID 40192532, 2025). "A study investigated the connection between Diabetes Mellitus (DM) and EC, focusing on the role of DM-associated genes in WFS1 in the alliance." (PMID 41312167, 2025). "Heterozygous mutations in the WFS1 gene have been described in association with non-insulin-dependent diabetes mellitus (OMIM: 125853) and Wolfram-like syndrome (OMIM: 614296) with autosomal dominant inheritance patterns." (PMID 39859454, 2025). "The clinical phenotypes associated with WFS1 mutations were diverse, with WS and diabetes (including common types of diabetes and MODY) being the most prevalent." (PMID 40641032, 2025). "And the WFS1 variant (c.985T>A/p.F329I) segregated with diabetes and non‐diabetes individuals tested." (PMID 40641032, 2025). "In this study, a follow‐up investigation of three diabetes families with WFS1 mutations was conducted." (PMID 40641032, 2025). "In this study, we conducted an extensive investigation focusing on the diabetes-associated gene WFS1 in the context of EC." (PMID 39478865, 2024). "Future studies involving larger and more diverse cohorts are essential to further validate and enhance our understanding of the role of WFS1 variants in diabetes." (PMID 39221226, 2024). "As a gene associated with diabetes, WFS1 plays a pivotal role in modulating the glycolytic pathway in EC." (PMID 39478865, 2024). "Approximately half of WFS1 variants are homozygous, but autosomal dominant pathogenic WFS1 variants have also been identified, recessive WFS1 variants can also lead to syndromic and nonsyndromic diabetes." (PMID 39221226, 2024). "According to a single likely pathogenic variant in the WFS1 gene found in molecular testing (c.2149G>A), isolated diabetes mellitus was confirmed." (PMID 39766859, 2024). "In our study, we found that the expression of the diabetes-associated gene WFS1 was downregulated in EC, affecting various components of the tumor microenvironment and leading to a poorer prognosis for patients." (PMID 39478865, 2024). "In our study of 165 patients with early-onset unclassified diabetes, we identified two individuals with compound heterozygous WFS1 variants." (PMID 39221226, 2024). "By leveraging the TCGA database, we conducted a comprehensive analysis of the prognostic and immune implications of the diabetes-associated gene WFS1 in EC." (PMID 39478865, 2024).
diabetes (continued). "The demographic and clinical analysis of the five patients with P/LP WFS1 variants in our study has uncovered significant patterns that contribute to the understanding of diabetes phenotypes associated with WFS1 variants." (PMID 39221226, 2024). "WFS1 variants are also responsible for diabetes development in the setting of Wolfram Syndrome 1 (WS1), a rare neurodegenerative disorder with other classical features comprising central diabetes insipidus, optic atrophy, and neurosensorial deafness." (PMID 39201476, 2024). "Overall, our comprehensive analysis highlights the potential of WFS1, a diabetes-associated gene, as a promising diagnostic and prognostic biomarker for EC." (PMID 39478865, 2024). "Beyond VGSC variants, we identified WFS1 variants, that have been previously reported to alter protein function in peripheral neuropathy (PN) patients with diabetes mellitus." (PMID 39000354, 2024). "Whole-exome sequencing was performed on the probands, and RNA sequencing was performed on four patients, their parents with WFS1 variants, and four gender- and age-matched children with type 1 diabetes mellitus." (PMID 36967753, 2023). "Several WFS1 polymorphic variants have been associated with the risk of developing diabetes mellitus." (PMID 37859980, 2023). "The authors concluded that quantitative WFS1 gene deficiency predisposes carriers of single functional WFS1 copy to diabetes and metabolic syndrome and makes them susceptible to environmental factors such as HFD." (PMID 37859980, 2023). "Considering that obesity is a risk factor for diabetes associated with insulin resistance, we aimed to evaluate, in the present study, the association of these two WFS1 variants with obesity in individuals of different ethnicities." (PMID 37859980, 2023). "According to the literature, 88% of variants located in exon 8 of the WFS1 gene are associated with WS, characterized by diabetes, optic atrophy, and deafness." (PMID 38162681, 2023). "Our new observation is in addition to the already known predisposition to deafness and diabetes mellitus, which has been associated with the WFS1 p.Arg42* variant." (PMID 35206658, 2022). "Via whole-exome sequencing, we found a heterozygous, likely pathogenic variant in WFS1 (encoding wolframin endoplasmic reticulum [ER] transmembrane glycoprotein) which was inherited from her father who also had diabetes." (PMID 35227307, 2022). "The WFS1 gene is associated with Wolfram syndrome (diabetes insipidus, diabetes mellitus, optic atrophy, and deafness)." (PMID 35207731, 2022). "For example, a dominant WFS1 p.Trp314Arg variant causes mild diabetes in an autosomal dominant fashion." (PMID 36613674, 2022). "Recently, de novo heterozygous WFS1 mutations were identified as causing a neonatal syndrome characterized by diabetes with onset in the first months of life and other congenital features." (PMID 33967960, 2021). "Following CRISPR/Cas9 correction of WFS1 mutations in patients’ iPSCs, iPSC-beta cells showed dynamic glucose-stimulated insulin secretion and reversed pre-existing streptozotocin-induced diabetes after transplantation into mice." (PMID 33477961, 2021). "Mutations in the WFS1 gene, encoding Wolframin, are known to result in a spectrum of phenotypes including β-cell dysfunction and diabetes." (PMID 33967960, 2021). "Of note, a single heterozygous WFS1 mutation (p.Arg703Cys) was identified in a family with diabetes diagnosed early (14 years) and late (55 and 60 years) in life." (PMID 33879153, 2021). "The use of NGS has also led to the discovery of paternally-inherited mutations co-segregated with glucose and lipid traits and a novel mutation of WFS1 gene in the maternal pedigree with diabetes and deafness." (PMID 34630320, 2021). "Using the MODY panel, both maternal aunts were found to carry a mutation in the WFS1 (Wolfram syndrome type 1) known to be associated with diabetes and deafness." (PMID 34630320, 2021).